HMGN5 (high mobility group nucleosome binding domain 5)
Description:
Preferentially binds to euchromatin and modulates cellular transcription by counteracting linker histone-mediated chromatin compaction.
Synonyms: NSBP1; NBP-45
Tractability: PROTAC: UniProt records ubiquitination sites on it; ubiquitination databases record sites on it; its protein half-life has been measured.
Gene: Protein-coding gene on chromosome X (81,112,915 to 81,202,016, reverse strand). Ensembl gene ENSG00000198157.
Subcellular location: Nucleus
Subcellular location (Human Protein Atlas): Nucleoplasm; Mitochondria
Gene Ontology:
Molecular function: RNA binding; chromatin binding; nucleosomal DNA binding
Biological process: negative regulation of apoptotic process; positive regulation of cell population proliferation; positive regulation of gene expression; positive regulation of DNA-templated transcription; regulation of DNA-templated transcription; chromatin organization
Cellular component: nucleoplasm; nucleus; chromatin
Homologues: Orthologues: chimpanzee HMGN5 (95% identical), macaque HMGN5 (94% identical), mouse Hmgn5 (48% identical), rat Hmgn5 (47% identical), rat Hmgn5b (45% identical).
Diseases named in the same sentence as HMGN5 in open-access papers:
HMGN5 is named in the same sentence as 31 diseases in open-access papers, as found by Europe PMC text mining. Sharing a sentence is not in itself a finding about the gene and the disease. The quoted sentences say what the papers report.
breast carcinoma (11 papers, 2012 to 2025). "Overall, HMGN5 was found to be highly expressed in breast cancer tissue compared to normal tissue and was associated with a worse patient prognosis and outcome." (PMID 40507264, 2025). "In MDA-MB-231 cells, scratch assaying and qRT-PCR data show that ~70% HMGN5 mRNA downregulation inhibits cancer cell migration, consistent with its role in breast cancer progression." (PMID 40305283, 2025). "HMGN5 promotes the proliferation and invasion of breast cancer cells, and its knockdown increases apoptosis in breast cancer cells." (PMID 35615145, 2022). "HMGN5, as a potential oncogene, is highly expressed in breast cancer and hormone-induced mouse uterine adenocarcinoma." (PMID 34336645, 2021). "MMP-2 or (and) MMP-9 was downregulated in breast cancer, osteosarcoma, and renal carcinoma cells with the silence of HMGN5." (PMID 32596388, 2020). "Studies have shown that HMGN5 plays an important role in the metastasis of prostate cancer, bladder cancer, kidney cancer, and breast cancer." (PMID 31930127, 2019). "HMGN5 is involved in tumorigenesis and is considered to be an unfavorable marker in breast cancer." (PMID 40507264, 2025). "In addition to HMGN1, the expression of HMGN5 (formerly NSBP1) was found to be elevated four-fold in highly metastatic breast cancer cells compared with that in low metastatic cells." (PMID 24348831, 2014). "In addition to HMGN1, the expression of HMGN5 (formerly NSBP1) was found to be elevated 4-fold in highly metastatic breast cancer cells compared with that in low metastatic cells." (PMID 25060707, 2014). "A higher expression level of HMGN5 was found in cancerous tissues of prostate cancer, bladder cancer, renal cancer, and breast cancer compared to their respective nontumor tissues." (PMID 32596388, 2020).
bladder cancer (9 papers, 2015 to 2024). "Regarding the molecular and cellular functions of the interaction between HMGN5 and Hsp27, the dynamic effects of these two factors on bladder cancer cell EMT and invasion were examined." (PMID 32315283, 2020). "To further validate the dynamic effects of HMGN5 and Hsp27 on bladder cancer cells, we examined how HMGN5 and Hsp27 silencing affected bladder cancer cell invasion and EMT." (PMID 32315283, 2020). "Here, we demonstrate that HMGN5 and Hsp27 are highly-expressed in bladder cancer tissues and positively correlated with each other." (PMID 32315283, 2020). "As demonstrated by immunoblotting and IHC staining, the protein levels of HMGN5 and Hsp27 were higher in bladder cancer tissues." (PMID 32315283, 2020). "In bladder cancer, miR-186 markedly repressed cell proliferation and metastasis by targeting NSBP1 (also known as HMGN5), which can bind to nucleosomes with its nucleosomal-binding domain to make chromatin unfold, regulating the expression of many genes." (PMID 32195180, 2020). "Bladder cancer patients were divided into two groups based on the expression of Hsp27 or HMGN5 using the med ian expression value as the cutoff." (PMID 32315283, 2020). "In the present study, we observed consistent results that, HMGN5 and Hsp27 mRNA and protein levels were increased in bladder cancer tissues." (PMID 32315283, 2020). "HMGN5 interacts with Hsp27 to promote tumor growth in a bladder cancer xenograft model in nude mice." (PMID 32315283, 2020). "In contrast to HMGN5 or Hsp27 overexpression, HMGN5 or Hsp27 silencing significantly inhibited bladder cancer cell invasion and increased the E-cadherin expression and decreased Vimentin expression." (PMID 32315283, 2020). "To validate the predicted interaction between HMGN5 and Hsp27, we first examined their protein levels in four bladder cancer cell lines, J82, HT1376, RT4, and T24 by immunoblotting." (PMID 32315283, 2020). "HMGN5 is highly expressed in human bladder cancer, thus promoting bladder cancer cell proliferation and invasion." (PMID 32315283, 2020). "Similar to previous investigations, Hsp27 and HMGN5 mRNA expression was remarkably upregulated in 56 cases bladder cancer tissues, and the expression levels were positively correlated with each other." (PMID 32315283, 2020). "Lower Hsp27 or lower HMGN5 expression was related to a higher rate of overall survival in bladder cancer patients." (PMID 32315283, 2020). "More importantly, Hsp27 overexpression further enhanced the promoting effect of HMGN5 overexpression, suggesting that HMGN5 interacts with Hsp27 to modulate bladder cancer cell invasion and EMT." (PMID 32315283, 2020). "Recent emerging research has reported that HMGN5 is overexpressed in many human cancers and that HMGN5 is related to carcinogenesis in a variety of cancer models, including bladder cancer." (PMID 32315283, 2020). "We confirmed the interaction between HMGN5 and Hsp27; then, we examined the effect of HMGN5 and Hsp27 overexpression on bladder cancer cell invasion and EMT." (PMID 32315283, 2020). "Luciferase reporter assay showed that miR-186 targets NSBP1 3′-untranslated region (UTR) directly and suppresses NSBP1 (HMGN5) expression in human bladder cancer cells." (PMID 26290438, 2015). "HMGN5 silencing attenuated IL-6-induced bladder cancer EMT and bladder cancer cell invasion." (PMID 32315283, 2020). "Transwell assays revealed that HMGN5 or Hsp27 overexpression alone could significantly promote bladder cancer cell invasion and decrease E-cadherin expression and increase Vimentin expression." (PMID 32315283, 2020). "Silencing HMGN5 could induce G2/M phase arrest with the downregulation of Cyclin B1 in bladder cancer cells and prostate cancer cells." (PMID 32596388, 2020). "HMGN5 and Hsp27 have both been regarded as oncogenic factors in bladder cancer." (PMID 32315283, 2020). "Here, we investigated whether HMGN5 participates in IL-6-Hsp27-induced EMT in bladder cancer." (PMID 32315283, 2020).
bladder cancer (continued). "Similarly, the effect of HMGN5 silencing could be enhanced by Hsp27 silence, further suggesting that HMGN5 interacts with Hsp27 to modulate bladder cancer cell invasion and EMT." (PMID 32315283, 2020). "The cisplatin resistance of bladder cancer could be regulated by HMGN5 through PI3K/AKT signaling." (PMID 32596388, 2020). "Next, the dynamic effects of HMGN5 and Hsp27 on IL-6-independent- and IL-6-dependent EMT and invasion in bladder cancer cells were evaluated." (PMID 32315283, 2020). "HMGN5 interacts with Hsp27 to modulate IL-6-independent- or IL-6-dependent EMT and cell invasion in bladder cancer cells." (PMID 32315283, 2020). "HMGN5 interacts with Hsp27, in vitro and in vivo, to modulate cell invasion and EMT in bladder cancer cells." (PMID 32315283, 2020). "Upon IL-6 stimulation, HMGN5/Hsp27 modulates bladder cancer EMT and bladder cancer cell invasion via the STAT3/Twist signaling pathway." (PMID 32315283, 2020). "Conversely, HMGN5 and Hsp27 silencing synergistically inhibited EMT and invasion in bladder cancer cells." (PMID 32315283, 2020). "Herein, HMGN5 or Hsp27 overexpression significantly promoted EMT by increasing E-cadherin and decreasing Vimentin, and promoted the invasion of bladder cancer cells." (PMID 32315283, 2020). "To study how HMGN5 exerts its effects on bladder cancer cell invasion and epithelial-mesenchymal transition (EMT), a crucial issue during cancer metastasis, we performed protein-protein-interaction (PPI) analysis to search for factors related to HMGN5." (PMID 32315283, 2020). "In summary, we provide a novel mechanism and experimental evidence showing how the interaction between HMGN5 and Hsp27 affects bladder cancer cell invasion and EMT with or without IL-6." (PMID 32315283, 2020). "In bladder cancer, HMGN5 silencing could block the PI3K/Akt signaling pathway, therefore improving the chemical sensitivity of human bladder cancer cells to cisplatin, whereby the viability and invasion of these cells could be inhibited in vitro and in vivo." (PMID 32315283, 2020). "Thus, HMGN5 could interact with Hsp27 to promote bladder cancer EMT, therefore enhancing bladder cancer cell invasion." (PMID 32315283, 2020). "Thus, we hypothesize that HMGN5 may interact with Hsp27 to affect IL-6-induced EMT and invasion in bladder cancer by modulating STAT3 phosphorylation and STAT3 targeting of the Twist promoter." (PMID 32315283, 2020). "Moreover, HMGN5 could modulate IL-6-Hsp27-induced EMT and invasion in bladder cancer cells by regulating STAT3 phosphorylation and STAT3-mediated Twist transcription." (PMID 32315283, 2020).
osteosarcoma (9 papers, 2014 to 2022). A usually aggressive malignant bone-forming mesenchymal neoplasm, predominantly affecting adolescents and young adults. "A hypoxic environment is commonly found in solid tumors such as osteosarcoma and is likely to be associated with tumor metastasis, so we further explored the relationship between HMGN5 and the hypoxic environment." (PMID 31930127, 2019). "Next, reporter constructs containing either the wild-type (WT) HMGN5 3′-UTR or HMGN5 3′-UTR with mutation (MT) at the predicted miR-140-5p target sequence were cotransfected into osteosarcoma U2-OS cells and then transduction of Mimic NC, miR-140-5p mimics, anti-NC or anti-miR-140-5p." (PMID 28341864, 2017). "In osteosarcoma cells, cisplatin induced HMGN5 expression and its overexpression reduced in vitro drug sensitivity." (PMID 36319719, 2022). "Targeting HMGN5 by miR-140-5p sensitizes osteosarcoma cells to chemotherapy, suggesting a potential application of miR-140-5p in the prognosis and treatment of chemoresistant cancers." (PMID 35211417, 2022). "Our previous study found that HMGN5 is highly expressed in osteosarcoma tissues and knockdown of HMGN5 inhibits migration and invasion of U-2 OS and Saos-2 cells." (PMID 31930127, 2019). "In the next step, we plan to explore the effects of HIF1A and HMGN5 on osteosarcoma cell metastasis by injecting three groups of cells (Cherry-GFP, HIF1AOE-GFP, and HIF1AOE-HMGN5sh) into the tail vein of nude mice." (PMID 31930127, 2019). "It is suggested that HMGN5 is an important downstream factor for HIF1A to promote osteosarcoma metastasis." (PMID 31930127, 2019). "Our results extended previous observations and found that miR-140-5p in osteosarcoma enhanced the chemoresistance by up-regulating HMGN5-mediated autophagy, suggesting that miR-140-5p is a potential target of an adjuvant therapy for osteosarcoma patients." (PMID 28341864, 2017). "Given that HMGN5 was the target of miR-140-5p, we applied lentivirus system to over expression HMGN5 to explore the relationship between HMGN5 and miR-140-5p in the chemoresistance of osteosarcoma." (PMID 28341864, 2017). "All these results indicate that miR-140-5p and its downstream target gene HMGN5 can be used to prevent and treat the osteosarcoma chemoresistance in the future." (PMID 28341864, 2017). "We showed that HMGN5 is the direct target of miR-140-5p and overexpression of miR-140-5p in osteosarcoma cell lines increased the osteosarcoma cell chemoresistance." (PMID 28341864, 2017). "In conclusion, our data elucidated that miR-140-5p promoted autophagy mediated by HMGN5 and sensitized osteosarcoma cells to chemotherapy." (PMID 28341864, 2017). "More importantly, our previous study demonstrated that HMGN5-mediated autophagy contributed to chemoresistance in osteosarcoma cell lines U2-OS and MG6319." (PMID 28341864, 2017). "For example, overexpressing high-mobility group nucleosome-binding domain 5 (HMGN5) in osteosarcoma U2OS and MG63 cell lines can induce resistance against chemotherapeutic drugs such as doxorubicin, cisplatin, and methotrexate via inducing autophagy." (PMID 25402829, 2014). "Their work revealed that HMGN5-mediated autophagy contributes to chemoresistance in osteosarcoma." (PMID 35211417, 2022). "Increased expression of miR-140 could modulate cancer cell chemoresistance by targeting IGFBP-5 and sensitizes osteosarcoma cells to chemotherapy by promoting HMGN5-mediated autophagy." (PMID 34479600, 2021). "It is suggested that HMGN5 may be an important downstream factor for HIF1A to promote osteosarcoma metastasis." (PMID 31930127, 2019). "We speculated that HMGN5 may be a downstream factor of HIF1A which plays an important role in osteosarcoma metastasis under hypoxic conditions." (PMID 31930127, 2019). "Therefore, we plan to explore the relationship between HIF1A and HMGN5 in a hypoxic environment and its effect on osteosarcoma metastasis." (PMID 31930127, 2019).
osteosarcoma (continued). "Our results showed that upregulated HMGN5 in a hypoxic environment increased the expression of c-jun and finally increased the expression of MMP2 and MMP9, which was associated with migration and invasion of osteosarcoma." (PMID 31930127, 2019). "The detection of dysregulated miRNAs in cancer tissues identified that miR-140-5p is down-regulated in the chemo-resistant osteosarcoma tissues, and targets high-mobility group nucleosome binding domain 5 (HMGN5), which is a positive regulator of BECLIN1 and ATG5." (PMID 31861937, 2019). "In addition, we discovered a novel mechanism of autophagy regulated by non-coding miR-140-5p in osteosarcoma through direct binding at the 3′-UTR of the HMGN5 mRNA." (PMID 28341864, 2017). "By utilizing siRNA against HMGN5, we found that i depletion of HMGN5 could reverse the effect of miR-140-5p and lead to increase of chemosensitivity in osteosarcoma cell lines." (PMID 28341864, 2017). "In addition, HMGN5 was identified as the target gene of miR-140-5p in osteosarcoma and HMGN5-mediated autophagy played an important role in the miR-140-5p-mediated chemoresistance." (PMID 28341864, 2017). "In addition to HMGN5 and chemoresistance, our work revealed a novel regulatory function of miR-140-5p in osteosarcoma and autophagy." (PMID 28341864, 2017). "However, our studies found that miR-140-5p facilitated the chemoresistance of osteosarcoma through regulating HMGN5-mediated autophagy, promoting tumor in osteosarcoma." (PMID 28341864, 2017). "We found that HIF1A and HMGN5 were upregulated in osteosarcoma (OS) cells cultured in the hypoxic environment, and the results of overexpression and knockdown experiments showed that HIF1A upregulated the transcription factor GATA1 and further promoted the expression of HMGN5." (PMID 31930127, 2019).
prostate carcinoma (7 papers, 2012 to 2022). A carcinoma that arises from epithelial cells of the prostate gland. "Bcl-2 interacting protein 3 like or high-mobility group nucleosome binding domain 5 were validated as binding targets of miR-183-3p and involved in chronic systolic heart failure or prostate cancer, respectively." (PMID 32650835, 2020). "Since HMGN5 was found to regulate mitochondrial pathway apoptosis and Bcl-2 family protein in prostate cancer cells, we also performed the JC-1 assay to evaluate the role of HMGN5 in the apoptosis of glioblastoma cells." (PMID 32596388, 2020). "For instance, silencing HMGN5 increased the sensitivity of prostate cancer cells to ionizing radiation." (PMID 32596388, 2020). "Early study showed that nucleosome binding protein 1 (HMGN5/NSBP1) was abundantly expressed in prostate cancer." (PMID 22420896, 2012). "Apart from the PI3K/AKT pathway, it was reported that HMGN5 could activate the MAPK signaling pathway to exert its function in prostate cancer cells." (PMID 32596388, 2020). "Besides on-target cisplatin resistance, HMGN5 may also be involved in post-target resistance, as its knockdown in prostate cancer cells elicited apoptosis and G2-M cell cycle arrest, leading to the sensitization of ionizing radiation." (PMID 36319719, 2022).
clear cell renal cell carcinoma (3 papers, 2012 to 2019). "Previous studies have confirmed that HMGN5 regulates the expression of MMP2 and MMP9 via c-jun and then contributed to the migration and invasion of clear cell renal cell carcinoma (ccRCC) cells." (PMID 31930127, 2019).
glioma (3 papers, 2015 to 2021). A benign or malignant brain and spinal cord tumor that arises from glial cells (astrocytes, oligodendrocytes, ependymal cells). "Notably, 5/14 OPR-DEGs, including TDH, SSTR5, HMGN5, LGR6, and SEL1L3, also have different expressions between high-risk patients and low-risk patients in the TCGA PTEN-wt subgroup (p < 0.001), suggesting that they are associated with the prognosis of PTEN-wt glioma." (PMID 34336645, 2021).